LINC00491 (long independently transcribed non-coding RNA 491)
Synonyms: BC008363
Gene: Long non-coding RNA gene on chromosome 5 (102,604,220 to 102,671,765, reverse strand). Ensembl gene ENSG00000250682.
Diseases named in the same sentence as LINC00491 in open-access papers:
LINC00491 is named in the same sentence as 12 diseases in open-access papers, as found by Europe PMC text mining. Sharing a sentence is not in itself a finding about the gene and the disease. The quoted sentences say what the papers report.
colon adenocarcinoma (2 papers, 2022 to 2023). "LINC00491 promotes proliferation, migration, and invasion of colon adenocarcinoma cells, probably by recruiting miR-145 which targets PAI-1, thus playing an oncogenic role during colon adenocarcinoma pathogenesis." (PMID 36674481, 2023). "LINC00491 is a lncRNA that has been validated as an oncogene which promotes tumor progression of colon adenocarcinoma." (PMID 36105104, 2022).
liver cancer (2 papers, 2021 to 2023). An epithelial or non-epithelial malignant neoplasm that arises from the liver. "LINC00491 was highly expressed in liver cancer patients, associating with poor prognosis." (PMID 34876144, 2021). "LINC00491 was highly expressed in liver cancer cases, associating with poor prognosis." (PMID 34876144, 2021). "Taken together, ROCK1 knockdown reversed the promotion of LINC00491 on liver cancer cells malignant phenotype." (PMID 34876144, 2021). "This study examined the subcellular localization of LINC00491 in liver cancer cells." (PMID 34876144, 2021). "In addition, the expression of LINC00491 in various liver cancer cell lines was significantly higher as compared to the normal liver cells." (PMID 34876144, 2021). "This study initially investigated the biological function of LINC00491 in liver cancer." (PMID 34876144, 2021). "Overall, this study indicated that LINC00491 might play a promotion role in the development and metastasis of liver cancer through miR-324-5p/ROCK1." (PMID 34876144, 2021). "Thus, LINC00491 overexpression facilitated liver cancer progression in vivo." (PMID 34876144, 2021). "It was hoped that LINC00491 could be identified as an effective target for liver cancer treatment." (PMID 34876144, 2021). "LINC00491 might be a potential treatment target for liver cancer." (PMID 34876144, 2021). "LINC00491 might be a potential treatment target of liver cancer." (PMID 34876144, 2021). "Thus, LINC00491 might be a novel target for the treatment of liver cancer." (PMID 34876144, 2021). "LINC00491 was involved in some tumors development, but its function in liver cancer has not been reported." (PMID 34876144, 2021). "However, to the best of our knowledge, the biological functions of LINC00491 in liver cancer have not been reported." (PMID 34876144, 2021).
breast carcinoma (1 paper, 2021). "Several studies show that LINC00491 expression is positively correlated with the overall survival in various malignancies such as breast cancer and colorectal cancer." (PMID 34876144, 2021). "Several bioinformatic analyses based on endogenous RNA Networks show that LINC00491 is positively correlated with the overall survival in breast cancer and colorectal cancer patients." (PMID 34876144, 2021).
colon cancer (1 paper, 2020). "Survival analysis showed that higher expression of AC131571.1, ANO1‐AS2, ITCH‐IT1, ARHGEF26‐AS1, AP004609.1, LINC00491, KCNQ1OT1, MACROD2‐IT1, TSSC1‐IT1 or LINC00355 was correlated to poor OS in patients with colon cancer." (PMID 31965704, 2020).
endometrial cancer (1 paper, 2019). Primary or metastatic malignant neoplasm involving the endometrium (mucous membrane that lines the endometrial cavity). "Further studies are warranted to explore the biological function and reveal the molecular mechanism underlying the role of LINC00491, LINC00483, ADARB2-AS1, and C8orf49 in endometrial cancer." (PMID 31192139, 2019). "In this study, we identified a signature based on LINC00491, LINC00483, ADARB2-AS1, and C8orf49 to discriminate patients with endometrial cancer that are at increased risk for poor outcome in combination with the information related to TNM stage and type of neoplasm." (PMID 31192139, 2019).
lung adenocarcinoma (1 paper, 2022). A carcinoma that arises from the lung and is characterized by the presence of malignant glandular epithelial cells. "It has been reported that aberrantly expressed long non-coding RNA LINC00491 promotes malignancy in multiple tumors, while the role of LINC00491 in lung adenocarcinoma (LUAD) is little reported and the mechanism for regulating tumor progression has not been elucidated." (PMID 36496997, 2022).
non-small cell lung carcinoma (1 paper, 2021). A group of at least three distinct histological types of lung cancer, including non-small cell squamous cell carcinoma, adenocarcinoma, and large cell carcinoma. "LINC00491 has already been recognised as hub oncogene in non-small-cell lung cancer (NSCLC) and CA, but it has never been explored and validated in HCC." (PMID 34237706, 2021).
thyroid cancer (1 paper, 2023). "The results showed that the migration ability of tumor cells decreased significantly after LINC00491 knockdown compared to the control group, suggesting that LINC00491 plays an important role in ovarian and thyroid cancers." (PMID 37723560, 2023).
tumor (8 papers, 2019 to 2023). "Further experiments in LUAD cell lines and mouse models confirmed that LINC00491 facilitates cell proliferation, migration and tumor metastasis through Wnt signaling via degrading MTSS1." (PMID 36496997, 2022). "Consistent with the conclusion of the xenograft tumor growth experiments, the silence of LINC00491 dramatically decreased the lung metastasis capability of LUAD cells." (PMID 36496997, 2022). "Silencing LINC00491 in vitro and in vivo subsequently hindered cell migration, invasion, proliferation and tumor growth, respectively." (PMID 35399733, 2022). "Consistent with our study, one recent study suggested that LINC00491 promotes tumor growth and lung metastasis in mouse xenografts." (PMID 36338699, 2022). "Consistently with previous findings that MTSS1 is a tumor/metastasis suppressor, our study reveals that the LINC00491/MTSS1 axis facilitates tumor malignant progression via activating Wnt/β-catenin signaling." (PMID 36496997, 2022). "The tumor volume and weight from the LINC00491 overexpression group was significantly higher as compared to the control group (P < 0.01)." (PMID 34876144, 2021). "The analysis of the relationship between LINC00491 expression and the clinicopathological characteristics of liver patients suggested that high LINC00491 expression was closely correlated with poor tumor TNM stage and metastasis." (PMID 34876144, 2021). "The relative expression of LINC00491 in the tumor tissues was significantly higher as compared to the normal tissues (P < 0.0001)." (PMID 34876144, 2021). "High LINC00491 expression was significantly correlated with worse tumor TNM stage (P = 0.014) and positive lymph node metastasis (P = 0.010)." (PMID 34876144, 2021). "In accord with in vitro observations, tumor volume and tumor weight were both significantly decreased after knockdown of LINC00491." (PMID 34237706, 2021). "The in vivo role of LINC00491 in tumor growth and lung metastasis was evaluated." (PMID 34876144, 2021). "And LINC00491 could also be applied to distinguish normal tissues from tumor tissues at different histologic grades." (PMID 34237706, 2021). "LINC00491/MTSS1/β-catenin may act as a complex to facilitate tumor progression." (PMID 36496997, 2022). "In summary, our study revealed that LINC00491 expression is upregulated in LUAD and that high expression of LINC00491 is positively correlated with tumor metastasis and poor survival." (PMID 36496997, 2022). "Taken together, LINC00491 could modulate the expression of miR-188-5p and ZFP91 to facilitate PC tumor growth." (PMID 35399733, 2022).
cancer (3 papers, 2018 to 2023). A tumor composed of atypical neoplastic, often pleomorphic cells that invade other tissues. "No study so far has reported any association of LINC00536, AL391421.1 or LINC00491 with cancer." (PMID 30261893, 2018). "It has been reported that LINC00491 plays a cancer-promoting role in various other cancers as well." (PMID 37723560, 2023).
LINC00491 also shares sentences with these, for which no sentence is quoted: pancreatic cancer (2 papers); colorectal cancer (1).